PRORP (protein only RNase P catalytic subunit)
Description:
Catalytic ribonuclease component of mitochondrial ribonuclease P, a complex composed of TRMT10C/MRPP1, HSD17B10/MRPP2 and PRORP/MRPP3, which cleaves tRNA molecules in their 5'-ends. The presence of TRMT10C/MRPP1, HSD17B10/MRPP2 is required to catalyze tRNA molecules in their 5'-ends.
Synonyms: KIAA0391; MRPP3; COXPD54
Tractability: Small molecule: a structure with a bound ligand is known. PROTAC: ubiquitination databases record sites on it.
Gene: Protein-coding gene on chromosome 14 (35,121,842 to 35,277,622, forward strand). Ensembl gene ENSG00000100890.
Subcellular location: Mitochondrion
Subcellular location (Human Protein Atlas): Mitochondria; Nucleoplasm
Pathways (Reactome):
Metabolism of RNA: rRNA processing in the mitochondrion; tRNA modification in the mitochondrion; tRNA processing in the mitochondrion
Gene Ontology:
Molecular function: ribonuclease P activity
Biological process: mitochondrial tRNA 5'-end processing; tRNA processing
Cellular component: mitochondrial matrix; mitochondrial ribonuclease P complex; mitochondrion; mitochondrial nucleoid
Genetic constraint (gnomAD): Loss-of-function variants: 38 observed, 49.87 expected, observed/expected ratio (o/e) 0.76, 90% interval 0.59 to 1. The upper end of that interval is the gene's LOEUF score, 1, which puts it in group 4 of 6, group 1 being the genes least tolerant of losing a copy. Missense variants: 564 observed, 641.21 expected, observed/expected ratio (o/e) 0.88, 90% interval 0.82 to 0.94. Synonymous variants: 207 observed, 235.41 expected, observed/expected ratio (o/e) 0.88, 90% interval 0.78 to 0.99.
Gene-disease validity (ClinGen):
ClinGen rates the evidence that PRORP causes each of these diseases.
mitochondrial disease (autosomal recessive): Definitive.
Homologues: Orthologues: chimpanzee PRORP (99% identical), macaque PRORP (91% identical), pig PRORP (81% identical), dog PRORP (80% identical), mouse Prorp (77% identical), rat Prorp (76% identical), guinea pig PRORP (69% identical), rabbit PRORP (67% identical), tropical clawed frog PRORP (44% identical), zebrafish prorp (43% identical), Drosophila melanogaster mldr (24% identical), Caenorhabditis elegans coa-6 (15% identical).
Diseases named in the same sentence as PRORP in open-access papers:
PRORP is named in the same sentence as 17 diseases in open-access papers, as found by Europe PMC text mining. Sharing a sentence is not in itself a finding about the gene and the disease. The quoted sentences say what the papers report.
Perrault syndrome (7 papers, 2021 to 2025). Perrault syndrome (PS) is characterized by the association of ovarian dysgenesis in females with sensorineural hearing impairment. "Its function requires interactions with the RNAse-P endonuclease component PRORP (=MRPP3), where mutations are known to also cause a Perrault syndrome phenotype." (PMID 38397478, 2024). "In summary, we present genetic and functional evidence that bi-allelic variants in PRORP are associated with pleiotropic clinical presentations and that PRORP should be considered another gene associated with the Perrault syndrome clinical spectrum." (PMID 34715011, 2021). "Biallelic variants in PRORP are associated with a broad range of phenotypes, ranging from Perrault syndrome (with intellectual disability) in female patients and isolated SNHL in a male patient, to a severe global developmental delay with hypertonia and acquired microcephaly." (PMID 41191133, 2025). "Perrault syndrome presenting with hearing loss and POI has also been reported as a result of a homozygous variant in PRORP." (PMID 37148394, 2023). "As variants in other tRNA processing factors such as PRORP, HARS2, and LARS2 are a known cause of PRLTS, a common mechanism of disease pathogenesis begins to emerge for Perrault syndrome." (PMID 34943861, 2021). "Biallelic variants in Protein Only RNase P Catalytic Subunit (PRORP) have recently been associated with a newly defined syndrome, combined oxidative phosphorylation deficiency 54 (COXPD54) (MIM #619737), encompassing a phenotypic spectrum of Perrault syndrome and leukodystrophy." (PMID 37558808, 2023).
cardiomyopathy (1 paper, 2024). A disease of the heart muscle or myocardium proper. "Like POLRMT and TEFM, MRPP3/PRORP and ELAC2 are essential proteins with non-redundant functions that cause very early cardiomyopathy and premature death in mice that model that seen in the patient mutations." (PMID 38779771, 2024).
mitochondrial disease (1 paper, 2024). "We show that N6AMT1 is required for the translation of PRORP and TRMT10C, two subunits of the mitochondrial RNAse P which are central for mitochondrial gene expression, and which are also implicated in mitochondrial disease." (PMID 39503847, 2024).
tumor (1 paper, 2023). "This analysis revealed a significant enrichment in the YC:YR ratio in the responsive tumor samples over the non-responsive samples for each gene, but particularly for C9orf85 and PRORP." (PMID 37996663, 2023).
PRORP also shares sentences with these, for which no sentence is quoted: Intellectual disability (3 papers); developmental delay (2); hearing loss (2); myocardial infarction (2); Alzheimer disease (1); autism (1); cancer (1); coronary artery disease (1); leukodystrophy (1); microcephaly (1); neurodegenerative disease (1); ovarian insufficiency (1); sensorineural hearing loss (1).